PCDH19 (protocadherin 19)
Diseases named in the same sentence as PCDH19 in open-access papers (continued):
Sharing a sentence is not in itself a finding about the gene and the disease.
developmental delay (8 papers, 2018 to 2026). "Here we describe a non-sense variant at the PCDH19 (c.498C>G; p.Y166*) in the Chinese male that exhibited early developmental delay and frequent seizures starting from the age of 5 months." (PMID 32425876, 2020).
epilepsy syndrome (8 papers, 2021 to 2025). A syndrome that has a characteristic cluster of clinical features and/or lectroencephalographic (EEG) findings that reflect underlying epileptic activity. "Protocadherin 19 (Pcdh19) is a member of the δ2-protocadherin family of homophilic cell adhesion molecules and one of the most common human genes linked to epilepsy syndrome." (PMID 39175067, 2024). "PCDH19 mutations result in an epileptic syndrome known as EIEE9 (OMIM # 300088)." (PMID 34261484, 2021). "Protocadherin 19 (PCDH19) gene is one of the most common genes involved in epilepsy syndromes." (PMID 35111125, 2021). "Supporting the notion that clusters may not be related to SUDEP risk is the PCDH19-Related Epilepsy Syndrome." (PMID 33643216, 2021).
status epilepticus (7 papers, 2009 to 2026). Status epilepticus is defined as a continuous seizure lasting more than 30 min, or two or more seizures without full recovery of consciousness between any of them. "Both patients with a PCDH19 mutation shared similar clinical features including the presence of both partial and generalized seizure types, occurrence of status epilepticus and mental retardation." (PMID 22848613, 2012). "Less than half (6/13) of the PCDH19-DS patients had status epilepticus although this is a highly frequent feature in SCN1A-DS (93/113, p<0.007)." (PMID 19214208, 2009). "Although the clinical spectrum of PCDH19 mutation-positive patients can show an overlap with DS patients, the age at onset, the occurrence of status epilepticus, the absence of seizures, myoclonic seizures, and the long-term outcome are different." (PMID 38891919, 2024).
infantile epileptic encephalopathy (6 papers, 2009 to 2024). an epileptic condition characterized by epileptiform abnormalities associated with progressive cerebral dysfunction. "Loss-of-function of PCDH19 can result in a rare early infantile epileptic encephalopathy (MIM: 300088, EIEE9), which almost exclusively occurs in heterozygous females." (PMID 34976017, 2021). "Pathogenic COL2A1 variants have been associated with varying skeletal dysplasias, including achondrogenesis and hypochondrogenesis (OMIM 200610), while pathogenic PCDH19 variants have been associated with a female-restricted form of sporadic infantile epileptic encephalopathy (OMIM 300088)." (PMID 40225944, 2024).
Seizure (6 papers, 2019 to 2025). A seizure is an intermittent abnormality of nervous system physiology characterized by a transient occurrence of signs and/or symptoms due to abnormal excessive or synchronous neuronal activity in the brain. "As yet, PCDH19 mutations have been reported in hundreds of females; however, only 15 mosaic males were reported to exhibit epileptic seizures with the onset ranges between 6 and 31 months." (PMID 32425876, 2020).
cortical dysplasia (4 papers, 2019 to 2025). "In accordance with our findings, cortical dysplasia is a recurrent finding in PCDH19-CE, and acquired microcephaly has also been reported." (PMID 34201522, 2021).
encephalopathies (4 papers, 2021 to 2024). "Second, though this review focuses on the role of steroids and PCDH19 in the pathogenesis of CE, changes in the steroid pathway are linked to a variety of other encephalopathies and mental illnesses." (PMID 34575929, 2021). "In a previous study of PCDH19-related encephalopathy, we demonstrated altered gyrification in the parahippocampal and entorhinal regions, and diffusion abnormalities in the underlying white matter, but no alterations emerged in the hippocampus when it was examined as a whole." (PMID 38238304, 2024). "PCDH19 encephalopathy represents a model of genetically determined neural network based neuropsychiatric disease in which quantitative MRI-based findings correlate with the severity of clinical manifestations and had have a potential predictive value if analyzed early." (PMID 38238304, 2024). "However, PCDH19 encephalopathy remains rare, has its onset in the pediatric age and is associated with impaired cognitive function, which may pose challenges in systematically assessing psychiatric features." (PMID 38238304, 2024).
Anxiety (3 papers, 2017 to 2022). Intense feelings of nervousness, tension, or panic often arise in response to interpersonal stresses. "In addition, Pcdh19 mutant animals, particularly females, display preweaning behavioral changes, including reduced anxiety and increased exploratory behavior." (PMID 34272258, 2021). "In addition, the results of our EPM test also indicate reduced anxiety in our animals, which could therefore represent a behavioral characteristic of Pcdh19 mutant animals." (PMID 34272258, 2021). "Pcdh19 KO males only showed increased time spent in the open arms of the EPM, indicating reduced anxiety, when tested as adults." (PMID 34272258, 2021). "However, when they repeated the test 23 weeks later, Pcdh19 HET females spent significantly more time in the center of the open field arena, suggesting reduced anxiety." (PMID 34272258, 2021).
early infantile epileptic encephalopathy (3 papers, 2019 to 2023). "PCDH19 variants cause early infantile epileptic encephalopathy 9 (EIEE9) with typical clusters of febrile and afebrile focal seizures." (PMID 36970534, 2023).
hepatocellular carcinoma (3 papers, 2018 to 2022). A malignant tumor that arises from hepatocytes. "For example, the methylation of PCDH19 served as a hallmark for predicting a poor prognosis of hepatocellular cancer." (PMID 32530136, 2020).
Klinefelter syndrome (3 papers, 2019 to 2023). A sex chromosome disorder caused by the presence of an extra X chromosome in the male karyotype. "In support of the cellular interference hypothesis came the DEE9 diagnosis for some male patients with a mosaic expression of PCDH19, due to a post-zygotic somatic mutation in their unique PCDH19 allele or to the mutation in one of the two PCDH19 alleles in the context of Klinefelter syndrome (XXY)." (PMID 33352832, 2020).
schizophrenia (3 papers, 2019 to 2023). A major psychotic disorder characterized by abnormalities in the perception or expression of reality. "Some studies have found schizophrenia and other psychotic disorders as a later‐onset manifestation of PCDH19‐GCE." (PMID 31714027, 2019).
attention deficit-hyperactivity disorder (2 papers, 2020 to 2024). A disorder characterized by a marked pattern of inattention and/or hyperactivity-impulsivity that is inconsistent with developmental level and clearly interferes with functioning in at least two settings (e.g. at home and at school). "Attention deficit hyperactivity disorder (ADHD) was described in 4/104 (PCDH19, CHD2 and MBD5)." (PMID 38279250, 2024).
breast carcinoma (2 papers, 2018 to 2024). "To determine the effect of NHRs on PCDH19 expression we screened a set of breast cancer cell lines to identify one that expresses ERα, PGR and AR." (PMID 38280856, 2024).
craniofrontonasal syndrome (2 papers, 2022 to 2024). "A further reinforcement of the pathogenicity of a heterozygous gain of dosage of PCDH19 comes from the fact that this mechanism has already been described in craniofrontonasal syndrome (CFNS)." (PMID 39457436, 2024).
Down syndrome (2 papers, 2022 to 2024). "Other than Down syndrome, the commonest known cause with a birth prevalence of ∼1/1,000 live births, other much rarer syndromes include Angelman, ARX, Coffin-Lowry syndrome, Cornelia de Lange, Fragile X, PCDH19, Prader–Willi, and Rett and Williams syndromes." (PMID 36090348, 2022).
early-onset epilepsy (2 papers, 2020 to 2023). "Therefore, women with early-onset epilepsy should pay special attention to the detection of the PCDH19 gene." (PMID 33287870, 2020).
Epileptic spasm (2 papers, 2022). A sudden flexion, extension, or mixed extension-flexion of predominantly proximal and truncal muscles that is usually more sustained than a myoclonic movement but not as sustained as a tonic seizure. "In this series, 8/36 patients (22.2%) had epileptic spasms, including those with KCNT1, SCN2A, SCN1A, DOCK6 and PCDH19 variants." (PMID 35715422, 2022).
microcephaly (2 papers, 2021). A congenital or acquired developmental disorder in which the circumference of the head is smaller than normal for the person's age and sex. "In addition, three of the five patients (60%) with PCDH19 mutation revealed abnormal brain MRI, including mesial temporal sclerosis, multiple white matter nodules over subcortical and periventricular regions, and microcephaly." (PMID 34833120, 2021).
Alzheimer disease (1 paper, 2022). A progressive, neurodegenerative disease characterized by loss of function and death of nerve cells in several areas of the brain leading to loss of cognitive function such as memory and language. "This population of hyperactive neurons might trigger seizures associated with Alzheimer’s disease and possibly a similar phenomenon is taking place in PCDH19 mosaic mice." (PMID 35741068, 2022).
fragile X syndrome (1 paper, 2025). A genetic syndrome caused by mutations in the FMR1 gene which is responsible for the expression of the fragile X mental retardation 1 protein. "The clinical trials for ganaxolone included patients with various conditions such as Fragile X Syndrome, CDKL5 deficiency disorder, CSWS, Lennox-Gastaut, and PCDH19." (PMID 40787618, 2025).
Lennox-Gastaut syndrome (1 paper, 2025). Lennox-Gastaut syndrome (LGS) belongs to the group of severe childhood epileptic encephalopathies. "Overall, the data suggest that ganaxolone is efficacious in reducing seizure frequency in a variety of disorders, including CDKL5, Lennox-Gastaut syndrome, and PCDH19 patients." (PMID 40787618, 2025).
liver cancer (1 paper, 2022). An epithelial or non-epithelial malignant neoplasm that arises from the liver. "Several studies have shown that PCDH genes are also involved in liver cancer development, including PCDH10, PCDH17, PCDH19, PCDH20, PCDHGC4, and PCDHGC5." (PMID 36230503, 2022).
metastatic disease (1 paper, 2025). "The upregulation of genes encoding matrix associated factors including proteases and cell adhesion molecules such as ADAM12, NTN3, LRRC15, CDH17, PCDH19, VTN highlighted the relevance of the tumor microenvironment and cell–cell and cell–matrix interaction for progression to metastatic disease." (PMID 41402347, 2025).
myopia (1 paper, 2025). "The other two examples are PCDH19-related neurodevelopmental disorder (MIM #300088) and ARR3-related early-onset high myopia (MIM #301010)." (PMID 40490530, 2025).
nasopharyngeal carcinoma (1 paper, 2016). A carcinoma arising from the nasopharyngeal epithelium. "In addition, the peptides tested (BMPER, PCDH19, Int β4 and Eps 1) significantly inhibited adhesion of strain WU2 to the D562 nasopharyngeal carcinoma-derived cell line, also widely used in studying the interaction of S. pneumoniae with the host cells." (PMID 26990554, 2016).
partial seizures (1 paper, 2019). "The girl with this mutation had fever sensitivity, clustered transient partial seizures, and developmental retardation, the clinical characterization was highly consistent with PCDH19‐GCE." (PMID 31714027, 2019).
prion disease (1 paper, 2022). A transmissible disease that is caused by a protein that is able to induce abnormal folding of normal cellular proteins, leading to characteristic spongiform brain changes, which are associated with neuronal loss without an inflammatory response. "Given the important role of PCDH19 in the maintenance of neuronal homeostasis and neuronal connections, its downregulation observed in scrapie animals could be associated with earlier onset and/or the augmented progression of the prion disease." (PMID 35252421, 2022).
psychotic disorder (1 paper, 2019). An abnormal condition of the mind that involves a loss of contact with reality. "The clinical spectrum of PCDH19 mutation includes PCDH19 Girls Clustering Epilepsy with or without mental retardation, psychosis, and asymptomatic male." (PMID 31714027, 2019). "The phenotypes of PCDH19 mutations include PCDH19‐GCE with or without mental retardation, psychosis, and male asymptomatic carriers." (PMID 31714027, 2019).
scrapie (1 paper, 2022). A fatal disease of the nervous system in sheep and goats, characterized by pruritus, debility, and locomotor incoordination. "Of all the selected genes, significant changes between the control and scrapie animals were found in the expression of five genes: PCDH19, SNCG, WDR45B, PEX1, and CABIN1." (PMID 35252421, 2022). "We identified many DMRs between the control and scrapie animals, some of them belonging to genes with possible neuroprotective roles against neurodegeneration (SNCG and WDR45B) and to genes that may facilitate or contribute to scrapie disease progression (PCDH19, PEX1, and CABIN1)." (PMID 35252421, 2022).
neurodevelopmental disorder (11 papers, 2018 to 2025). A behavioral and cognitive disorder with onset during the developmental period that involves impaired or aberrant development of intellectual, motor, or social functions. "Among these, only PCDH19 and SRPX2 have been demonstrated to cause neurodevelopmental disorder and/or seizures, while a missense variant in CSTF2 gene has been proposed to cause mild speech delay and learning difficulties in affected males." (PMID 39457436, 2024). "In the nervous system, CDH13 togetherwith PCDH19 is found in synaptic space controlling vital neuronal processesincluding axonal outgrowth and synaptic formation, consistent with their geneticcontribution to a number of neurodevelopmental disorders." (PMID 38629124, 2024). "PCDH19 was a member of the delta-cadherin (δ-cadherin) superfamily genes, and the δ-cadherin superfamily included a family of differentially expressed neuro-adhesion molecules involved in a range of neurodevelopmental disorders." (PMID 36970538, 2023). "This duplication contains 17 genes, of which only the PCDH19 and SRPX2 genes have been related to neurodevelopmental disorders, while for the CSTF2 gene, this relationship is provisional." (PMID 39457436, 2024).
neurological disease (6 papers, 2015 to 2025). "Clustering Epilepsy (CE) is a neurological disorder caused by pathogenic variants of the Protocadherin 19 (PCDH19) gene." (PMID 38454084, 2024). "PCDH19 (Protocadherin 19), a member of the cadherin superfamily, is involved in the pathogenic mechanism of an X-linked model of neurological disease." (PMID 26450854, 2015). "The relevance of protocadherin family in human pathology is demonstrated by many reports and by the fact that human PCDH19, as member of δ-Protocadherin family is clearly involved in pathogenic mechanism of a neurological disease." (PMID 26450854, 2015). "Pathogenic PCDH19 variants cause the debilitating neurological disorder CE." (PMID 38454084, 2024). "In addition to PCDH19, the defective function of other δ-PCDHs has been associated with neurological disease." (PMID 34201522, 2021). "Although the mechanisms by which PCDH variants lead to neurological disorders are not fully understood, insights from the well-studied PCDH19 suggest that its unique X-linked inheritance pattern may disrupt cellular adhesion affinities, an occurrence potentially exacerbated by X-inactivation." (PMID 40870033, 2025). "Additionally, in view of the reduction in allopregnanololone and other steroid levels in patients with protocadherin 19 (PCDH19)—female limited epilepsy, trial is currently ongoing to evaluate if ganaxolone may be beneficial in patients with this rare neurological disorder." (PMID 33321734, 2020).
genetic disease (4 papers, 2018 to 2024). "PCDH19-related epilepsy is a rare genetic disease caused by defective function of PCDH19, a calcium-dependent cell–cell adhesion protein of the cadherin superfamily." (PMID 34201522, 2021).
cancer (2 papers, 2012 to 2024). A tumor composed of atypical neoplastic, often pleomorphic cells that invade other tissues. "An interesting gene in cancer cells grown as a co-culture with the CAFs is the up-regulated protocadherin 19 (PCDH19)." (PMID 22453032, 2012). "Perhaps the increased risk of cancer in epileptic patients is caused by the PCDH19 mutation and over-expression, not however related to drugs toxicity." (PMID 22453032, 2012). "For the purposes of the microarray data validation, we have randomly selected 3 of all the genes that may play the most important role in the cancer cells-CAFs interactions: PCDH19, DSP and MAG." (PMID 22453032, 2012).
PCDH19 also shares sentences with these, for which no sentence is quoted: autism spectrum disorder (3 papers); infantile-onset epilepsy syndrome (3); Rett syndrome (3); Rolandic epilepsy (3); Asperger syndrome (2); childhood-onset epilepsy syndrome (2); focal epilepsy (2); mental illnesses (2); 22q11.2 deletion syndrome (1); Angelman syndrome (1); Atrophy (1); bacterial infection (1); behavioral disorders (1); channelopathies (1); Christianson syndrome (1); Coffin-Lowry syndrome (1); encephalitis (1); Fever (1); Focal cortical dysplasia (1); generalized epilepsy (1); generalized seizures (1); glioblastoma (1); hypogonadism (1); Infantile onset (1); infection (1); infectious encephalitis (1); Jeavons syndrome (1); Landau-Kleffner syndrome (1); lymphoma (1); Miller-Dieker syndrome (1).
A further 16 diseases each share a sentence with PCDH19 in 1 paper.